GZMB (granzyme B)
Diseases named in the same sentence as GZMB in open-access papers (continued):
Sharing a sentence is not in itself a finding about the gene and the disease.
tumor (continued). "IL-15 has an essential role in NK cell proliferation and survival and promotes NK cell anti-tumour effector function via stimulation of IFN-γ, granzyme B and perforin production." (PMID 34888493, 2021). "Then the expression of perforin and Granzyme B was validated in in vitro model of MDSC culture, ex vivo experiments of MDSCs isolated from tumor-bearing mice, and MDSCs from human." (PMID 33868318, 2021). "Both the primary and distant tumor tissues of SPNpro-injected mice exhibited higher MFIs (3.0- and 4.2-fold, respectively) of FITC-labelled anti-granzyme B antibodies than that for SPN-1- or SPN-2-injected mice." (PMID 34006860, 2021). "Both cryo-thermal Mφs and cryo-thermal DCs increased the level of granzyme B in CD4+ T cells compared to the tumor-bearing group, but DCs from cryo-thermal therapy with DFO treatment decreased the level of granzyme B in CD4+ T cells." (PMID 34209797, 2021). "Granzyme-B, the functional marker of CD8+ T cells, was also increased in the combination treatment groups, indicating that VPA/HPTA activated the CD8+ T cells and thus enhanced the RT effect in the tumor, which may be associated with IL-12 secreted by anti-tumor M1-type macrophages." (PMID 34054811, 2021). "Tumor infiltrating lymphocytes (TILs), especially the infiltration of CD4+ GzmB+ T cells in the central region of the tumor was identified to be positively correlated with the prognosis of the patients." (PMID 34631551, 2021). "In the current study, we have evaluated whether the granzyme B targeting peptide biomarker, [18F]AlF-mNOTA-GZP, is able to stratify responders to ICI therapy in the HEPA 1-6 syngeneic model of HCC, using flow cytometry to correlate tumour biomarker retention with tumour-associated immune cells." (PMID 35936114, 2021). "CD20 (+) B cells in the tumor microenvironment can produce IFN-γ, interleukin 12p40, granzyme B, and TRAIL and acted in cooperation with CD8 (+) T cells to promote tumor immunity and predict good prognosis in HCC." (PMID 34484330, 2021). "Higher percentage of CD107a+, GzmB+ and IFN-γ+ tumor-infiltrating NK cells were observed respectively in PVRIG-deficient mice." (PMID 34174928, 2021). "Both esCAR Tpre and esCAR Tpost cells released similar amounts of IFNγ, granzyme B, and GM-CSF when exposed to CD19+ tumor cells." (PMID 33526841, 2021). "Here, we report an increased high-avidity of tumor antigen-specific CD8+ T cells in the spleen from KV-treated animals, alongside increased Granzyme B expression and elevated proliferation, TNF-α and IFN-γ secretion." (PMID 34885215, 2021). "Of the five GSDM gene members, only GSDMD expression showed a positive correlation with CD8+ T cell marker genes (e.g., CD8A, CD8B, PRF1, GZMA, GZMB, and IFNG) in CTLs across all three tumor cohorts." (PMID 34429144, 2021). "Blocking IL-9 signaling reduced the expression of granzyme B and perforin in human CD8+ T cells, and stimulation with recombinant IL-9 enhanced the cytotoxicity of tumor-specific mouse CD8+ T cells." (PMID 33777008, 2021). "In our study, co-treatment of DSF and anti-PD-1 Ab noticeably elevated the population of granzyme B-positive CD8+ TIL and synergistically inhibited tumor growth compared to monotherapy." (PMID 34858816, 2021). "Meanwhile, CD8+ T cells were induced to secrete granzyme B to restrain tumor, and CD31 immunofluorescence staining also indicated that the tumor vessels became sparse." (PMID 34054811, 2021). "GzmB blockade abrogated CD8 T cell tumoricidal activity, but converted Treg cells maintained their ability to kill tumor cells." (PMID 33976133, 2021). "And in tumor microenvironment, the interaction between PD-L1 and PD-1 can inhibit IFN-γ, TNF-α and granzyme B secretion in T cells." (PMID 34522232, 2021). "LY3039478 significantly enhanced IFN-γ+CD8+, Granzyme B+CD8+, and TNF-α+CD8+ T-cell proportions from tumour tissues compared with a control group." (PMID 32778818, 2020).
tumor (continued). "In particular, we focused on genes associated with cytotoxic lymphocyte phenotype and function (CD3, CD8, Interferon-γ, Granzyme B, Perforin, and IL-2 receptor B/CD122) as well as IL-6 and IL-6 receptor given our serum ELISA and tumor PCR results for IL-6." (PMID 32084139, 2020). "Expression of membrane receptors such as FCGR3A and CX3CR1, and cytotoxic genes like GZMB, FGFBP2, PRF1, and GNLY increased gradually during this transition, implying a gradually acquired tumor-killing ability in CD56dim NK cells." (PMID 33298893, 2020). "Given that iNKTs are relatively rare, both in circulation and within the tumor, increasing their numbers and function (such as an increase in IFN-γ production and upregulation of granzyme B) should be safe." (PMID 32560408, 2020). "Flow cytometric analysis demonstrated that provision of hetIL-15 resulted in higher proportion of tumor-infiltrating CD8+ and CD4+ T lymphocytes, as well as NK cells harboring GzmB in comparison to untreated mice (respectively)." (PMID 32461349, 2020). "Knockdown of IL-1β decreased tumor growth and reversed TAM immune suppression while increasing the frequency of polyclonal CD8 T cells and their production of IFNγ and Granzyme B." (PMID 33584701, 2020). "In the spleen and early on among tumor-infiltrating immune cells, NK cells constituted the vast majority of granzyme B+ cells, with only a very small proportion of CD3+ T cells expressing granzyme B, as determined by fluorescence-activated cell sorting (FACS)." (PMID 33220234, 2020). "Densities of CD8+, CD8+ Granzyme B+, CD8+ programmed death-1-positive (PD-1+) and programmed death-ligand 1-positive (PD-L1+) cells were higher in post- versus pre-vaccination tumor tissue." (PMID 32500232, 2020). "Tumor‐specific T‐cell responses that develop in the presence of a chronic LCMV infection exhibit diminished T‐bet and granzyme B expression, indicating that these cells are altered in effector cell formation." (PMID 32220007, 2020). "Analysis of intracellular cytokine expression showed that compared to corresponding WT mice, the tumor-infiltrating CD8+ T cells of CCR2KO mice produced increased amounts of IFN-γ and granzyme-B." (PMID 33322474, 2020). "Upon infiltration into the tumor, T cells resistant to TGFβ demonstrate increased cytotoxicity and expression of effector differentiation markers including Ly6C+, CD62L−, and granzyme B+." (PMID 32273499, 2020). "FACS analysis revealed that tumor‐infiltrating CD8+ T cells in the MB treatment group secreted more IL‐2, granzyme B, and perforin (Fig EV4E)." (PMID 32391629, 2020). "“Pushing” tumours (n = 26) and “Infiltrating” tumours (n = 16) that had plenty PD-1+CD8+ TILs in IM were analysed for CD8, PD-1, TIM3, Granzyme-B (GZMB) and Ki67." (PMID 32616847, 2020). "Tumor-residing Tregs are capable of inducing apoptosis in NK and CD8+ T cells in a granzyme B and perforin-dependent manner." (PMID 33519807, 2020). "LDHA abrogation in the murine B16F10 melanoma model improved response to anti-PD-1 treatment, accompanied by an increase in tumor infiltration of CD8+ T cells and NK cells, increase in production of IFN-γ and granzyme B, and decrease in Treg infiltration." (PMID 33324565, 2020). "We found that MB treatment dramatically enhanced expression of perforin, granzyme B (GZMB), and IL‐2 by CTL in tumor nodules." (PMID 32391629, 2020). "The results revealed that HA2 FMG is able to highly induce tumor regression and also promote the lymphocyte proliferation, CD8+ T cells cytotoxicity, IFN-γ and granzyme B induction, along with a decline in anti-inflammatory cytokines level." (PMID 32782438, 2020). "Combination therapy promoted IFNγ production by CD4+ T cells in the tumor and CD8+ T cells in the spleen and granzyme B production by CD8+ T cells in the tumor." (PMID 33256806, 2020).
tumor (continued). "Compared to those on CD4+ T cells in PBMCs, the expression levels of antitumor (TNFβ, T-bet, and granzyme B) and protumor (PD-1 and IL-10) markers on CD4+ T cells in tumor sites were commonly higher." (PMID 32117733, 2020). "Tumor tissue was stained and examined for CD8, granzyme B, PD-1, and PD-L1 positivity to draw conclusions on therapy response." (PMID 33072556, 2020). "The interaction of CD103 with E-cadherin on tumor cells optimizes cytokine release in CD8+ T cells, since siRNA targeting E-cadherin partially inhibits IFN-γ and granzyme B production." (PMID 32974219, 2020). "Consistent with a more pro-inflammatory TME, a higher frequency of tumor-infiltrating CD8+ T cells co-expressing NKG2D, Granzyme B, and IFNγ was observed in bintrafusp alfa-treated animals." (PMID 32373533, 2020). "CD8+ T cells and CD3+ T cells liberate anti-tumor molecules such as interferon-γ (IFN-γ) and IL-2, and cytotoxic molecules perforin and granzyme B are also secreted by effector CD8+ T cells, making them effective to kill tumor cells." (PMID 33182298, 2020). "Similar approach was shown to increase in granzyme B+IFN-γ+CD8+ T-cells and a decrease in immunosuppressive tumor-infiltrating cells including PMN-MDSCs, Tregs, and M2 macrophages." (PMID 32499785, 2020). "Cytokine changes and increases in cytotoxic activity, such as granzyme B and FAS expression, were evident, suggesting that G-CSF plays a role in both T helper and cytotoxic T cell activity in the tumor microenvironment." (PMID 33042110, 2020). "We also found that in the combination PD-1 antibody and evodiamine treatment group, tumor-infiltrating CD8+ T cells showed stronger activation phenotypes and more increased IFN-γ, TNFα and Granzyme B (GrzmB) production." (PMID 33208183, 2020). "Clinicopathological factors, tumor-infiltrating lymphocytes (TILs), CD4+ and CD8+ T cells, and granzyme B (GZB) expression in resected HCC, and postoperative overall and progression-free survival were compared between the three groups." (PMID 32075608, 2020). "Tumor cell-derived TGF-β acts on CTLs to specifically repress the expression of perforin, granzyme B, and FasL and to reduce the production of IFN-γ, resulting in a significant attenuation of CTL-mediated tumor cytotoxicity." (PMID 32695181, 2020). "In the ABACUS trial, the tumor samples with an inflamed phenotype were analyzed for dual CD8+ cells and Granzyme B staining, founding that responding tumors expressed more cells dually stained compared to relapsing ones (87 vs. 30% of dual expression)." (PMID 33194654, 2020). "Meanwhile, tumour-infiltrating lymphocytes (TILs: CD8+ T and NK cells) from Gsdme−/− tumours also expressed less granzyme B (GzmB), perforin (PFN), interferon-γ (IFNγ), and TFN." (PMID 32404864, 2020). "High-Dose AA and Anti-PD1 Treatment Combination Leads to Increase in Tumor CD8+ T Cell and Macrophage Infiltration, Enhanced Granzyme B Production by Cytotoxic Cells, and Enhanced Interleukin 12 Production by Antigen-Presenting Cells." (PMID 31911474, 2020). "Granzyme B and perforin were examined as cytotoxic factors while FAS and Fas ligand (FasL) were examined as tumor apoptotic markers." (PMID 33042110, 2020). "GW6471 combined with PD-L1 blockade strongly increased the number of tumor antigen-specific CD8+ T effector cells (OT I tetramer+) and highly boosted the production of granzyme B (GrmB), perforin, and IFN-γ from CD8+ T cells." (PMID 33086073, 2020). "Activation of T cells was observed and tumor killing activity was noticed in 6 PDOs by assessing interferon‐gamma (IFNG), granzyme B (GZMB), and perforin‐1 (PRF1) of CD3+TILs, data that is consistent with clinical trials for different cancer types." (PMID 33042756, 2020). "hetIL-15 directly affects NK, CD8+ and CD4+ T cells within the tumor promoting their proliferation, survival and cytotoxic commitment, with high levels of IFN-γ production and upregulation of GzmA, GzmB and perforin." (PMID 32461349, 2020).
tumor (continued). "In the context of tumor microenvironment, tumor-derived MAIT cells secreted less IFN-γ, IL-17 and granzyme B, perforin, but they secreted more IL-8, which is of great importance in promoting tumor angiogenesis and progression." (PMID 32015682, 2020). "It indicates, that lactic acid prevents tumor infiltration by IFN-γ and granzyme B producing T and NK cells, which promote tumor immune evasion and growth." (PMID 31035592, 2019). "These cells included effector T cells (granzyme B+ CD8+), which are indicative of anti‐tumour immunity." (PMID 31709774, 2019). "This treatment promoted tumor growth, and resulted in lower percentages of tumoral CD8+ cells and granzyme B+ and IFNγ+CD8+ T cells." (PMID 31780645, 2019). "Immunohistochemistry for CD4, CD8, Foxp3, Granzyme B (GZMB), PDL1, and HLA class I was performed in tumor biopsies collected before and after DC vaccination." (PMID 31649669, 2019). "Further, on day 10 of combination treatment, the number of activated (CD8+ CD69+) T cells in the tumor were increased and T-cell functions were enhanced, with an up-regulated expression of the effector T-cell markers, IFN-γ, Granzyme B, and KLRG1." (PMID 31781498, 2019). "Increased intracellular levels of GZMB and higher levels of extracellular LAMP1 (CD107a) in tumor-infiltrated CD8+ T cells indicate better targeting and killing capacity of cancer cells by CTLs." (PMID 31710308, 2019). "Tumor cells exhibited an expression of CD5 (two cases), CD8 (three cases), CD56 (six cases), CD57 (three cases), and Granzyme B (eight cases)." (PMID 32372136, 2019). "Of note, when eosinophils were co-cultured with tumor cells, a marked polarization of EPX, ECP, and granzyme-B to the immune synapses was observed selectively in IL-33 EO." (PMID 31717819, 2019). "The vaccine showed efficient tumor eradication in several tumor models with enrichment of IFN‐γ+, TNF‐α+, and granzyme B+ tumor‐infiltrating lymphocytes." (PMID 30937265, 2019). "Despite their high cytolytic activity, hypoxic CAR-T cells produced relatively low levels of granzyme B, IFN-γ, IL-2, and IL-6 in response to transfected cells and tumor cell lines endogenously expressing the target antigen." (PMID 31052261, 2019). "Expression levels of perforin, granzyme B, IFN-g, TNF-a, and IL-2 in CD8+ tumor-infiltrating lymphocytes (TILs) were significantly lower than those in CD8+ T cells of peripheral blood." (PMID 30682105, 2019). "Beside granzyme B and perforin, γδ T cells can also utilize death receptor ligands, among them TRAIL, to mediate cytotoxicity against tumor cells." (PMID 31555275, 2019). "As a consequence of elevated numbers of these cells in tumor, an increased amount of interferon gamma (IFN-γ) and granzyme B is observed." (PMID 31035592, 2019). "Consistent with the cytotoxic activity, Ly6C+CD8+ population from EMT6 tumor-primed mice expressed higher levels of IFNG, GZMA, GZMB, and PRF1 as assessed by qPCR analyses." (PMID 30926774, 2019). "We successfully developed a granzyme B delivery system with a GrB-T core and an HA/PMPC shell for site-specific tumor treatment that simulated CTL/NK cell-mediated cancer immunotherapy." (PMID 31695790, 2019). "In fact, we observed substantial expression of granzyme-B and EPX in tumor-infiltrating EO induced by in vivo exposure to IL-33, at variance with control mice." (PMID 31717819, 2019). "In the host immune responses against pathogen infection and tumor, CD8+ T cells exert cytotoxicity against target cells by releasing perforin and Granzyme B." (PMID 31316301, 2019). "We also compared the expression levels of perforin, granzyme B, IFN-g, TNF-a, and IL-2 of CD8+ T cells between PBMCs and tumor in each T cell subset." (PMID 30682105, 2019). "Similar to the CT-26 model, MC38 tumors showed a significant increase in GzmB+ and PD-1+ CD8+ T-cells indicative of a cytolytic response to the tumor." (PMID 31779705, 2019).
tumor (continued). "As opposed to controls, tumor tissues from IL-33-treated mice displayed the substantial presence of degranulating tumor-infiltrating eosinophils within tumor necrotic areas, as revealed by co-expression of Siglec-F with EPX and granzyme-B." (PMID 31717819, 2019). "NK cells from obese mice and humans are less responsive to tumor target cells in terms of cytotoxicity and production of IFN-γ, granzyme B, and perforin." (PMID 32038612, 2019). "NK cells exert its function on pathogens, tumor cells, stressed hepatocytes, and HSCs via the production of cytokines (IFN-γ, TNF-α, IL-10, IL-12, IL-22, etc.)and cytotoxic molecules (granzyme B, Perforin, etc.)both in direct or indirect fashion." (PMID 31500589, 2019). "Consistent with the data of mRNA quantification, the Granzyme B expression in 4/21 ICR-CAR T cells was higher than in the control and 4/7 ICR-CAR T cells, especially in the CD4+ subset, after tumor cell stimulation." (PMID 31379876, 2019). "Overall, no drastic change in the immune cell infiltrate into distant tumor lesions was observed in RFA-pretreated patients, as exemplified by stainings with CD45RO (activated lymphocytes) and granzyme B (cytotoxic lymphocyte effectors)." (PMID 31803175, 2019). "In addition, paclitaxel, cisplatin, doxorubicin could upregulate the expression of mannose-6-phosphate receptor (M6PR) on the surface of tumor cells, thereby increasing the permeability of cell membrane to granzyme B, making the cytotoxicity of lymphocytes to tumor cells independent of perforin." (PMID 30519541, 2018). "NKs can rapidly respond to the presence of tumor cells and initiate an antitumor immune response by producing effector molecules such as IFN-γ, perforin, and granzyme B." (PMID 30443251, 2018). "The regulatory T cells from the tumor microenvironment were also able to induce cell death of NK cells and CD8 T cells that required Granzyme B and perforin." (PMID 29032503, 2018). "The presence of granzyme B+/perforin- CD8+ T cells demonstrated an opposite pattern among PBMC, SN, and tumor." (PMID 29966014, 2018). "A set of tumor cytotoxic genes were up-regulated in CIK cells, including GZMB, FASL, PRF1, TNFα, CD40L, and IFN-γ." (PMID 30333226, 2018). "In contrast, the fractions of granzyme B+/perforin+ CD8+ T cells in SN were below 6% (p<0.001 vs PBMC and tumor)." (PMID 29966014, 2018). "Consistent with increased infiltration of cytotoxic T cell populations, we also observed more IFN-r+ and Granzyme B+ functional CD8+ T cells and less Eomes+ exhausted CD8+ T cells in FASN inhibitor-treated OvCa tumor." (PMID 30619288, 2018). "Tumour cells are CD3+, either CD4+ (more commonly) or CD8+, or in rare instances CD4−/CD8−, whilst those expressing CD8 have a cytotoxic profile (TIA1+, granzyme B±)." (PMID 30305106, 2018). "Functionally, co-culturing T4 cells with tumor cells following chemotherapy resulted in an increase in intracellular tumor Granzyme B, possibly implicating M6PR as a ‘gateway’ for Granzyme B to enter the tumor." (PMID 30167862, 2018). "QIF is used to simultaneously measure the level of CD3+ tumor infiltrating lymphocytes (TILs), in situ T-cell proliferation (Ki-67 in CD3) and effector capacity (Granzyme-B in CD3)." (PMID 30097571, 2018). "When applying a 5% PD-L1 tumor-nest cut-off, 70% of samples segregated to the high PD-L1 group, with CD8, Granzyme B, and CD68 significantly higher in those samples (P < 0.05)." (PMID 29874226, 2018). "Perforin inhibition significantly reversed both baseline and AZD1775-enhanced KIL control of MOC2 tumor cells, suggesting that AZD1775 enhanced granzyme B-dependent control of MOC2." (PMID 29925431, 2018). "Our results are in agreement with a previous study in which higher expression of IL-2, TNF-α, and granzyme B in CAR T cells was also observed, when similarly made CAR T cells were co-cultured with target tumor cells with EGFR or EGFRvIII." (PMID 29685162, 2018).